TNF (tumor necrosis factor)
Diseases named in the same sentence as TNF in open-access papers (continued):
Sharing a sentence is not in itself a finding about the gene and the disease.
cancer (continued). "Furthermore, a characteristic of cancer is the hypercoagulable state induced by the cytokine storm, whereby excessive local release of procoagulants, such as tumor necrosis factor (TNF)-a, interleukin (IL)-1, and IL-6, results in a hypercoagulable state." (PMID 36555410, 2022). "In addition, Lim’s study showed that TNF-α is a major factor that triggers cancer cell immunosuppression in response to T cell surveillance by stabilizing PD-L1 via the p65/CSN5 signaling axis." (PMID 35260434, 2022). "Conversely, depletion of ADCK2 largely inhibited TNFα-induced HIF-1α stability in cancer cells." (PMID 36439873, 2022). "A Study have shown that andrographolide can promote the production of IL-2 and lymphocytes, and IL-2 activates the cytotoxic activity of NK cells, CD8 + T cells and lymphokine-induced killer cells, and produces TNF-α, which increases the cytotoxicity of lymphocytes to cancer cells." (PMID 36238575, 2022). "They secrete paracrine factors such as tumor necrosis factor (TNF), WNT10A, platelet-derived growth factor alpha (PDGFA), and neuregulin 1 (NRG1) to sensitize sensory neurons, thereby promoting neuropathic pain associated with various cancers." (PMID 35067780, 2022). "TNF-α also activates Src protein tyrosine kinase, a regulator of endothelial permeability, which is involved in the extravasation of cancerous cells, promoting angiogenesis, proliferation, and invasion of cancer cells." (PMID 35252243, 2022). "In particular, serum levels of interleukin-6 (IL-6) and tumor necrosis factor-α (TNF-α) may be increased as part of the host response to tissue damage or cancer treatments." (PMID 35331230, 2022). "Further study on TNFα-induced nSMase2 activation in cancer cells may shed light on the role of TNFα and sEV in cancer progression." (PMID 35050379, 2022). "Moreover, EXO-OVA-mAb also increased the level of IFN-γ and TNF-α in both serum and tumors, and thus enhancing cancer therapeutic effect." (PMID 36733388, 2022). "Therefore, the concentration of 10 ng·mL−1 of TNF‐α used in this study mimicked the proinflammatory environment in cancer condition." (PMID 34197030, 2022). "Yet, the role of TNF-α in cancer progression is still a matter of debate." (PMID 36376825, 2022). "The equine ACFCs nucleofected with the BPV-E1^E4 gene construct displayed significant deregulation of s higher number of pathways than BPV-E4 transgenic ACFCs, such as the FoxO signaling pathway, the PI3K-Akt and TNF signaling pathways, and Proteoglycans in cancer." (PMID 35216085, 2022). "In addition, studies have shown that the loss of NFKB1 can lead to inflammation and the progression of cancer by increasing the expression of TNF." (PMID 35127830, 2022). "Moreover, the function of lncRNA H19/miR-204-5p/NF-κB/FLIP axis was investigated in vitro, and the antigastric cancer effect of TP plus TNF-α was proved in the mice xenograft model." (PMID 36110523, 2022). "Furthermore, other moieties, such as high mobility group box protein 1 (HMGB1), which induce TNFα expression in cardiac myocytes were also increased in cancer cachexia models." (PMID 35326491, 2022). "The incidence of cancers reported during follow-up appointments (median of 4 years), was 4.2% for tofacitinib users and 2.9% for TNFα users, with a hazard ratio of 1.48 (tofacitinib:TNFα)." (PMID 36110853, 2022). "Additionally, SSD demonstrated a strong ability to block TNF-α-induced cancer cell invasion and angiogenesis in HUVECs while triggering death in HeLa cells by accelerating the loss of the mitochondrial membrane potential." (PMID 36547471, 2022).
cancer (continued). "Additionally, TNF and IL-17 signaling pathways, as well as pathways in cancer and transcriptional misregulation in cancer, were also significantly enriched in both groups." (PMID 35628542, 2022). "Meanwhile, tumors upregulated autophagy levels in cancer cells through activating surrounding monocytes in concert with monocyte-derived TNF and IL1B, and monocyte-induced autophagy promoted EMT of cancer cells but also promoted tumor metastasis by activating NFKB-SNAI1 signaling pathway." (PMID 36531059, 2022). "In addition, the release of IFN-γ and tumor necrosis factor α (TNF-α) by CTLs induces cytotoxicity of cancer cells." (PMID 35303904, 2022). "Interestingly, these cells also appeared to be regulated by TNF signaling, with increased apoptosis and programming cell death, suggesting a conflicting mode of cancer growth and active immune surveillance in the S components." (PMID 35874770, 2022). "The role of TNF-α in cancer development is a double-edged sword." (PMID 36578029, 2022). "Inflammation, cancer, and immunological illnesses may all be traced back to the main active molecules inside organisms, such as TNF-α and IL-6, which perform integral roles in the pathogenesis of these conditions." (PMID 36032961, 2022). "Likewise, in the combination treatment group, much higher levels of serum cytokines like IFN-γ and TNF-α that play vital roles in cellular immunity against cancer were observed." (PMID 35595770, 2022). "To conclude, the two seemingly opposing effects of the TNFα-TNFR network on cancer progression may be actually inter-connected, and eventually the pro-metastatic functions of the TNFα-TNFR family members possibly dominate their anti-malignancy effects." (PMID 35663982, 2022). "Third, growth factors and cytokines such as TNF-α, vascular endothelial growth factor and IL-6 induced by the inflammatory response could promote the proliferation and metastasis of residual cancer cells." (PMID 35194147, 2022). "The low level of TNFα in patients could be a reason for the poor outcome of a single IAP antagonist in treating cancer in previous clinical trials." (PMID 36119107, 2022). "Additionally, the use of fucoidan (400 mL/day) has also been used as an anti-inflammatory agent in cancer patients where it demonstrated a reduction in cytokines including IL-6, TNF-a and IL-1β after its oral administration." (PMID 36501043, 2022). "Human TNF-α, also termed cachectin, was initially believed to be critical in cancer cachexia." (PMID 35319749, 2022). "Of note, the correlations between TNF mutations and survival were not discovered in any type of cancer by Cancer Genome Atlas (TCGA) analysis, indicating that although TNF acts as another cytotoxic factor, its effect is not as sufficient as IFN-γ." (PMID 36189283, 2022). "The role of anti-TNFα monoclonal antibodies such as infliximab in cancer is still debated." (PMID 35504900, 2022). "CD70 belongs to the tumor necrosis factor (TNF) family which is critical in cancer immunotherapy." (PMID 36497225, 2022). "For instance, TNF-α induces secretion of KARS1 from cancer cells to the extracellular space." (PMID 35501376, 2022). "Similarly, regarding angiogenesis in cancer, TNF-α can also induce both antiangiogenic and proangiogenic actions in different tumors." (PMID 36324671, 2022). "Baicalein has been revealed to activate multiple mechanisms to manage cancer development and progression by modulating cell signaling pathways, including those related to inflammation, cell cycle, angiogenesis, apoptosis, autophagy, and tumor necrosis factor." (PMID 36432119, 2022). "TNF-alpha is a cell signaling protein (cytokine) involved in apoptotic cell death by extrinsic apoptotic signaling pathway via death domain receptors and in the promotion and progression of cancer, including TNBC cells." (PMID 35260587, 2022).
cancer (continued). "Moreover, KEGG pathway analysis revealed that propionate treatment affected apoptosis, the TNF signaling pathway, and transcriptional misregulation in cancer." (PMID 34972816, 2022). "In the analysis of KEGG pathways of DEGs, we found different regions of skin under black hair showed great differences in Focal adhesion, Tyrosine metabolism, PI3K-AKT signaling pathway, Proteoglycans in cancer, TNF signaling pathway, MicroRNAs in cancer, etc.." (PMID 36507537, 2022). "TNFα mediated apoptosis, a form of cell-death, is the desired outcome for cancer therapeutics." (PMID 36240239, 2022). "The development of cancer is usually accompanied by inflammation and cancer development and metastasis can be inhibited by treating or controlling inflammation and blocking the production of related factors (e.g., TNF-α, IL-6, IL-17, etc.)." (PMID 36686662, 2022). "For instance, coexpression of hERG and tumour necrosis factor receptor 1 (TNFR1) has been found at the cell membrane of both SKBR3 and SH-SY5Y cell lines, suggesting a hERG role in recruiting TNFR1 to the membrane, therefore enhancing TNF-α-induced cancer cell proliferation." (PMID 36422154, 2022). "TNFα produced by macrophages was found to promote cancer cell sphere formation in vitro." (PMID 36276076, 2022). "Preclinical studies of TNF and TNFi show varying effects on cancer cells and cancer immunity, which adds to the complexity of how these agents may impact the efficacy of ICI when used to treat irAE." (PMID 36081549, 2022). "Intriguingly, it is reported that nuclear PD-L1 translocation could promote the transcription of GSDMC and switches the apoptosis induced by TNF-α to pyroptosis in cancer, which further indicated the relationship between pyroptosis and immune checkpoint." (PMID 35047095, 2022). "At this point, it is unclear whether cancer-derived TNFα directly affects the liver in vivo since it is possible that immune cells activated in the presence of cancers could also be a source of TNFα1." (PMID 35705545, 2022). "Enrichment analysis showed that 735 GO analysis and 85 KEGG pathways were mainly involved in biological processes such as response to the drug, inflammatory response, gene expression, and cell proliferation and apoptosis, as well as signal pathways such as cancer, TNF, HIF-1, and T cell receptor." (PMID 35265149, 2022). "In addition, the KEGG analysis indicated that the up-regulated mRNAs were significantly related to TNF signaling, spliceosome, ribosome, proteoglycans in cancer, phagosome, and C-type lectin receptor signaling pathway." (PMID 36090276, 2022). "There was no increased risk of cancer seen with any of the individual TNF inhibitors in RA patients when bDMARDs were added to the previously existing conventional DMARD therapy." (PMID 36289670, 2022). "Intersection targets mainly regulated biological processes and related pathways, such as the regulation of cell death (GO:0010941), the regulation of cell migration (GO:0030334), the pathways in cancer (ko05200), IL-17 signaling pathway (ko04657), and TNF signaling pathway (ko04668)." (PMID 36415861, 2022). "TNF-α is primarily considered to enhance acute immunological responses in cancer immunotherapy." (PMID 35159388, 2022). "Taken together, our data show that non-responsiveness to primary SARS-CoV-2 mRNA vaccination mainly occurs in cancer patients, while IBD patients, who initially respond to the vaccine, show an early antibody loss particularly when treated with TNF-α inhibitors." (PMID 35634285, 2022). "We found that “PI3K-Akt signaling pathway,” “MAPK signaling pathway,” “Proteoglycans in cancer,” “IL-17 signaling pathway,” “Cellular senescence,” and “TNF signaling pathway” may be the potentially critical mechanism of PD anticolon cancer." (PMID 36003525, 2022).
cancer (continued). "A recent meta-analysis summarized 54 studies and suggested that peripheral blood inflammatory markers (CRP, TNF and IL-6) were significantly related to cancer-related DepS and might be helpful for management of DepS in the cancer patients." (PMID 36615742, 2022). "TNF has also contradictory effects in cancer progression due to its two receptors." (PMID 36611932, 2022). "TNF‐α appears to bear a mediating influence in the development of insulin resistance in cancer, and so the anti‐inflammatory effect of exercise may be of some benefit." (PMID 36251564, 2022). "KEGG pathway analysis revealed that JSK might produce anti-SCI effects via multiple signaling pathways, including those in cancer, and the TNF, HIF-1, Toll-like receptor, and PI3K-Akt signaling pathways." (PMID 35265147, 2022). "However, a later study demonstrated that a major effect of autophagy in cancer cells is to inhibit TNFα and TRAIL-induced apoptosis by reducing FADD-dependent caspase-8 activation." (PMID 35401556, 2022). "It has been postulated that TNF-α executes a pivotal function in inflammation and cancer." (PMID 35954156, 2022). "For example, antibiotics can kill microbiota to reduce the level of LPS and the related TNFα and thus could attenuate the response of cancer patients to an IAP antagonist therapy." (PMID 36119107, 2022). "TNF-α particularly, as a major cytokine from the N1 neutrophil, enhances the transmigration of neutrophil and released nitric oxide (NO), which induced apoptosis in cancer cells and inhibited cancer growth." (PMID 35267547, 2022). "Cancer-associated adipocytes (CAA) are characterized by a smaller size, they secrete more chemokine ligand 2 and 5 (CCL2, CCL5), IL-1β, IL-6, leptin, VEGF and TNF-α, but lower the expression of adiponectin." (PMID 35741450, 2022). "Through these gap junctions, 2′3′-cyclic GMP-AMP (cGAMP) is secreted by cancer cells to reprogram astrocytes that give rise to a pro-inflammatory program, characterized by the production of a variety of cytokines (e.g., IFNα and TNF)." (PMID 35884845, 2022). "Consequently, upon TNF-induced caspase-8 activation, caspase-8 cleaved GSDMC at 362 LELD 365 to release a pore-forming N-terminal domain causing cancer cell pyroptosis." (PMID 35608339, 2022). "The underlying mechanism is that inflammatory processes are involved in regulating the relationship between social support and cancer mortality, with patients at higher levels of social support and satisfaction having lower levels of inflammatory factors, including IL-6, TNF-α, CRP, and VEGF." (PMID 36091116, 2022). "The KEGG pathway enrichment of the darkturquoise module was found to include mainly MAPK signaling pathway (p.adjust = 1.26E-07), PI3K-Akt signaling pathway (p.adjust = 1.14E-04), TNF signaling pathway (p.adjust = 6.92E-09), and transcriptional misregulation in cancer (p.adjust = 2.70E-05)." (PMID 36034872, 2022). "During the progression of the disease, cancer cells change the properties of surrounding cells, forcing them to produce growth factors and proinflammatory cytokines, such as TNF-α, IL-1β, and TGF-β, that accelerate the acquisition of a mesenchymal-like phenotype during EMT." (PMID 35884974, 2022). "A variety of signaling pathways including TNF-α, KRAS, IL-6/JAK/STAT3, IL-2/STAT5, epithelial-mesenchymal transition, oxidative phosphorylation, and mTOR were found to be significantly associated with TRPs in pan-cancer." (PMID 35831825, 2022). "Chronic inflammation caused by the interaction of myeloid-cell-derived ROS with tumor necrosis factor-alpha (TNF-α)-mediated signaling may contribute to cancer progression." (PMID 35884547, 2022).
cancer (continued). "Previous reports suggest that high levels of exogenous lactate can affect cell motility, so in this work, we used a wound healing assay in which cells were pretreated with LA for 24 h to analyze the effect of lactic acid on the response of cancer cells to TNF-α." (PMID 36555705, 2022). "This occurrence, of NBTE in cancer patients especially, is due to the damaged state of endothelial cells from the constant interaction between macrophages, monocytes, interleukins, TNF, and tissue factor, creating a surface for platelet aggregation, thus inducing a hypercoagulable state." (PMID 36555410, 2022). "IL-6, TNF- α are inflammatory markers and their elevated level promotes cancer progression." (PMID 36330087, 2022). "The systemic inflammatory response of cancer prompts neutrophil infiltration, resulting in the secretion of interleukin-2 (IL-2), interleukin-6 (IL-6), interleukin-10 (IL-10), tumor necrosis factor α (TNF-α), and vascular endothelial growth factor (VEGF)." (PMID 35407463, 2022). "Similar to TGF-β, TNF-α plays a twin role in malignant tumors." (PMID 36146567, 2022). "Evidence indicates that serum levels of IL-6 and TNF-α may be elevated in several cancers, and both proinflammatory cytokines present dichotomous since they have function that maintains the body's homeostasis." (PMID 35646122, 2022). "IL-6, IL-8, or TNF-α production by DCs stimulated by commensal bacteria, demonstrated in this study, may be associated with IBD and cancer." (PMID 35739324, 2022). "To identify the unrevealed lncRNA that might participate in TP/TNF-α–induced antigastric cancer effect, we screened the generally accepted lncRNAs that related to NF-κB activation." (PMID 36110523, 2022). "As the name suggests, TNF activates the immune system help to kill cancer cells." (PMID 35337149, 2022). "IL-1, IL-6, and TNF-α play an essential role at the systemic level as inducers of cancer cachexia." (PMID 36072935, 2022). "However, studies on serum TNF-α in patients with CRC found that these concentrations increased with the stage of cancer and higher mortality." (PMID 36005576, 2022). "TNF-α could enhance the production of VEGF by modulating the inflammatory process and upregulating several genes associated with cancer invasion and metastasis." (PMID 36497431, 2022). "Additionally, KEGG analysis revealed that all common genes were mainly enriched in pathways in cancer, proteoglycans in cancer, T cell receptor signaling pathway and TNF signaling pathway." (PMID 35637248, 2022). "Thus, the cell-free synthesized human TNF-α showed significant anticancer potency and selective cytotoxicity against test cancer cell lines." (PMID 35205024, 2022). "The NK cells release reactive oxygen and nitrogen species which kill cancer cells via tumor necrosis factor (TNF)-related apoptosis-inducing ligand (TRAIL)-dependent or perforin dependent mechanisms, respectively, in an attempt to further eliminate cancer cells." (PMID 35327484, 2022). "In conclusion, the network pharmacology of this study was used to screen out the active compounds of SBG (baicalein and wogonin), 41 intersection targets (VEGFA, IL6, MAPK3, JUN, TNF, and other targets), and 20 main pathways (Pathways in cancer, IL-17, TNF signaling pathway and others)." (PMID 36415861, 2022). "Inflammation is an effective inducer of EMT in tumor cells and may induce cancer cells to produce pro-inflammatory factors, such as IL-6, IL-8, and TNF-α." (PMID 35735628, 2022). "Notably, iron homeostasis is also central in inflammatory responses, whereby NF-κB, TNF and NLR are known to be important regulators and have been implicated in cancer-related inflammation." (PMID 36685915, 2022).